MIR30E (microRNA 30e)
Synonyms: hsa-mir-30e; MIR30E*; MIRN30E; mir-30e
Gene: MicroRNA gene on chromosome 1 (40,754,355 to 40,754,446, forward strand). Ensembl gene ENSG00000198974.
Gene Ontology:
Biological process: miRNA-mediated post-transcriptional gene silencing
Cellular component: RISC complex
Homologues: Orthologues: chimpanzee ptr-mir-30e (100% identical), macaque mml-mir-30e (99% identical), pig ssc-mir-30e (82% identical), dog MIR30E (67% identical), zebrafish mir30e-2 (65% identical), zebrafish mir30a (64% identical), tropical clawed frog xtr-mir-30d (63% identical), zebrafish mir30d (57% identical). Paralogues in human: MIR30A (61% identical), MIR30D (55% identical), MIR30B (37% identical), MIR30C1 (34% identical), MIR30C2 (32% identical).
Diseases named in the same sentence as MIR30E in open-access papers:
MIR30E is named in the same sentence as 2 diseases in open-access papers, as found by Europe PMC text mining. Sharing a sentence is not in itself a finding about the gene and the disease. The quoted sentences say what the papers report.
esophageal cancer (1 paper, 2016). A primary or metastatic malignant neoplasm involving the esophagus. "Follow-up experiments indicated transfection of MIR20b, MIR30e, MIR498 and MIR196 affected the apoptotic pathway in esophageal cancers cells." (PMID 27462775, 2016). "Collectively, above results suggested that the four predicted miRNAs, MIR20b, MIR30e, MIR498 and MIR196 may be involved in the apoptotic pathway in esophageal cancers cells." (PMID 27462775, 2016).
tumor (1 paper, 2022). "Only MIR10B, MIR21, and MIR30E inherited RP scores of <10 and were thus chosen as candidate orthologs for further tumor classification analysis using the SVM model." (PMID 35765483, 2022).